IL4 (interleukin 4)
Diseases named in the same sentence as IL4 in open-access papers (continued):
Sharing a sentence is not in itself a finding about the gene and the disease.
atherosclerosis (continued). "In fact, potential therapies for the treatment of atherosclerosis such as mucosal administration of athero-antigens (HSP 65, oxLDL, apoB-100 peptides) have shown increments in production of IL-10, IL-4 and TGF-β." (PMID 29163168, 2017). "IL-4 is reportedly necessary for invoking a TH2 response and has been shown to play a role in the progression of atherosclerosis." (PMID 18795166, 2008). "IL-4 and IFN-γ are pro-atherogenic cytokines with a significant role in atherosclerosis." (PMID 39458984, 2024). "Moreover, IL-4/6 and NF-κB can also downregulate the expression of ABCA1 in macrophages and promote the development of atherosclerosis." (PMID 37670950, 2023). "Because IL-4 production is needed in cells that accumulate during atherosclerosis progression, but not in cells newly recruited during resolution, we next examined the abundance of IL-4-producing cells in plaques." (PMID 33720008, 2021). "In the present study, we aimed at determining the signals upstream of STAT6 that induce resolution of atherosclerosis and hypothesized that the classical activators of STAT6, IL-4, and/or IL-13 are involved." (PMID 33720008, 2021). "Our data thus far indicate that IL-4/13 are needed for atherosclerosis resolution, and the source of these cytokines is not from cells that are newly recruited in the resolution phase, but from cells accumulating during the disease progression phase." (PMID 33720008, 2021). "The role of IL-4 in atherosclerosis is controversial and gender-specific effects have not yet been described." (PMID 35097028, 2021). "Additionally, increasing IL-10, IL-4, IL-13, and TGF-β and reducing IL-1β, Il-6, TNF-α, CCL3, CCL4, and CCL5 can slow the progression of atherosclerosis." (PMID 32346605, 2020). "Moreover, the endothelial hypoxia-inducible factor-1α promoted atherosclerosis and monocyte recruitment by upregulating miR-19a7, while TNF-α or IFN-γ or IL-4 suppressed IL-10 in B cells (from patients with atherosclerosis) via upregulating miR-19a expression." (PMID 32308549, 2020). "By contrast, IL-4 delivery was not able to decrease atherosclerosis in murine models of atherosclerosis." (PMID 31191522, 2019). "Although considered to be a Th2 interleukin, IL-4 does not appear to be antiatherosclerotic, as IL-4−/− mice do not have increased atherosclerosis, and administration of IL-4 into ApoE−/− mice does not reduce development of atherosclerotic lesions." (PMID 22844641, 2012). "Although it has been assumed that IL-13 affects atherosclerosis in the same way as IL-4, no studies are currently available to support this notion." (PMID 23027612, 2012). "It was known that inflammatory cytokines such as interleukin-1 and −4 (IL-1 and IL-4) and tumour necrosis factor-α (TNF-α) may coordinately induce gelatinase enzymes during progression of atherosclerosis." (PMID 22716287, 2012). "IL-4/13 levels do not change during resolution of atherosclerosis." (PMID 33720008, 2021). "Production of IL-4/13 by newly recruited cells is not required for resolution of atherosclerosis." (PMID 33720008, 2021). "Since LPS, oxLDL, and IL-4 induce macrophage SLC37A2 protein expression, we speculate that induction of macrophage SLC37A2 expression promotes inflammation resolution and slows atherosclerosis progression." (PMID 34957260, 2021). "Considering the low expression of IL2 and IL4 mRNA in atherosclerotic plaques, the role of these cytokines may not be significant in atherosclerosis." (PMID 22509262, 2012). "In our study, in subjects prone to atherosclerosis but in a stable phase of the process as the type 2 diabetic patients studied, a significant increase of the Th2-profile-related IL-4 was observed whereas we did not evidence a reduction in circulating IFN-γ during treatment." (PMID 23259529, 2012).
atherosclerosis (continued). "However, exogenous injection or genetic deletion of il4 in another study did not affect lesion development regardless of the induction of atherosclerosis by a high fat diet or angiotensin II, indicating a possible case-specific requirement of the Th2 cytokine in atherosclerosis progression." (PMID 32849502, 2020). "In this study, mice in the ApoEST2DKO group, with significant atherosclerosis development, showed increased VCAM1 and ICAM1 levels and a non-significant but decreasing trend in IL-4 and IL-5, consistent with previously reported results." (PMID 38674885, 2024).
dermatitis (93 papers, 2009 to 2025). An inflammatory process affecting the skin. "Animal studies have shown that DEP exposure elevates Th2-type cytokines IL-4 and IL-13, changes associated with AD-like skin inflammation." (PMID 40115349, 2025). "AD is a skin disorder with both compromised skin barrier function and persistent itching symptoms, which is associated with elevated levels of IL-4 and IL-13." (PMID 37978564, 2023). "AD appears to be characterized by skin inflammation, barrier dysfunction, and chronic pruritus, which are all attributable to excessive activation of the IL-13/IL-4‒JAK‒STAT6/STAT3 axis and its associated immune reaction." (PMID 33233866, 2020). "Elevated IL-4 expression suppresses IgE production, causing induced skin inflammation." (PMID 40179089, 2025). "Moreover, p63 can help prevent particular dermatitis brought on by suppression of type 2 cytokines (interleukin 4 [IL-4] and IL-13) linked to keratinocyte development." (PMID 38584846, 2024). "MC903-induced skin inflammation was significantly reduced in the Raptor deficient or rapamycin-treated mice, accompanied by downregulation of IL-4 and reduced numbers of eosinophils, suggesting that mTORC1 is essential for the type 2 skin inflammation induced by MC903." (PMID 36983043, 2023). "Since TSLP receptors are expressed in various immune cells, including ILC2s, the TSLP-TSLP receptor interaction activates ILC2s to produce type 2 cytokines, such as IL-4, IL-5, and IL-13 and stimulates eosinophils, basophils, and dendritic cells, which eventually causes AD-like skin inflammation." (PMID 36983043, 2023). "Within the context of AD, type 2 cytokines such as interleukin- 4 (IL4), IL13, and IL31 are linked to the escalation of skin inflammation." (PMID 40420206, 2025). "The results showed that CBG improved dermatitis severity score, epidermal thickness, and mast cell count and reduced inflammatory cytokines (Tslp, Il1b, Il4, Il6, Il13, Il17, Il18, Il22, and Il33) by qRT-PCR (p < 0.001)." (PMID 39851511, 2025). "In Dfb-induced AD mice, UFB shower treatment improved the dermatitis score, downregulated the gene expression of AD-related inflammatory cytokines (IL-4 and IL-13), and upregulated skin barrier-related molecules." (PMID 39790997, 2024). "Additional processes contribute to the dermatitis caused by the cpd mutation of Sharpin, including TLR3 signaling, NLRP3 inflammasome and IL-1β signaling, and IL-4 signaling." (PMID 38156288, 2024). "The study found that cASC-EVs improved AD-like dermatitis, decreased serum IgE, ear thickness, and inflammatory cytokines such as IL-4 and IFN-γ in a dose-dependent manner." (PMID 37444013, 2023). "Then, we found that BIS attenuated the skin IL-4 release, which is a Th2 cytokine, and increased in patients with dermatitis." (PMID 35807237, 2022). "In a topical MC903 application model, basophil-derived IL-4 acts on skin-resident group 2 innate lymphoid cells (ILC2s), leading to enhanced proliferation of ILC2s and AD-like skin inflammation." (PMID 35693800, 2022). "Our previous study showed that oral administration of EsB, a solanocapsine-type glycoside and a major component in tomato juice, ameliorated experimental dermatitis in mice through decreases in IgE and ConA-mitogenic action, and a decline in IL-4 secretion." (PMID 35455695, 2022). "On the other way, the other study suggested that innate TLR2 signals convert transient T helper 2 cell-mediated dermatitis into persistent inflammation, as seen in chronic atopic dermatitis, through IL-4-mediated suppression of IL-1035." (PMID 35715478, 2022). "The researchers observed an increase in the severity of dermatitis with an increase in IL-2 and IL-17 expression levels and a decrease in the severity of dermatitis with a decrease in the expression of IL-4 and IL-10 expression levels." (PMID 35431950, 2022).
dermatitis (continued). "Depletion of basophils ameliorates eczematous skin inflammation with crusts and scales, suggesting the role of basophil-derived IL-4 in the formation of lichenized skin lesions." (PMID 35693800, 2022). "These cells, when activated, release pro-inflammatory cytokines, including IL-4, IL-13, and IL-31 which led to the dermatitis." (PMID 34948125, 2021). "Dupilumab, a human monoclonal antibody against IL-4 receptor alpha, blocks signaling of IL-4 and IL-13, improving severe dermatitis in AD patients." (PMID 33670758, 2021). "Accumulating evidence underscores the notion that AD can be re-defined as a form of skin inflammation attributable to excessive IL-13/(IL-4) signaling in individuals with atopic diathesis." (PMID 33233866, 2020). "It produces a marked reduction in dermatitis score and inflammatory cell infiltration; and decreased the production of IL-4, NO, PGE2, and TARC." (PMID 30658631, 2019). "Malt1-KO mice that develop skin inflammation were found to have increased serum levels of the pro-inflammatory cytokines IL-2, IL-4, IL-6, IL-17, IFN-γ, and TNF." (PMID 31632405, 2019). "The importance of the TH2 pathway is further supported by the observation that transgenic mice overexpressing the TH2 cytokines IL-4 or IL-13 spontaneously develop skin inflammation that is frequently used as an animal model for AD." (PMID 31447854, 2019). "DNCB-induced skin inflammation was accompanied by increases in serum IgE and IL-4 levels, and gracillin co-treatment inhibited these DNCB-induced increases by 48.6% and 71.4%, respectively." (PMID 30200442, 2018). "We found that the most relevant cytokines for the oxazolone model were IL-1β, TNFα, IL-4, and IL-6, which shared more than 25% of their variation with the variation in ear thickness in all dermatitis induced mice." (PMID 28290517, 2017). "Remarkably, germ-free mice responded highly in key parameters, such as total dermatitis score, ear thickness, TNFα, IL-4, and IL-5." (PMID 28290517, 2017). "This can be explained by the fact that skin inflammation in AD is predominantly mediated by Th2 cytokines (IL-4, IL-13) in the acute phase of the disease and that the Th2 cytokine milieu is known to suppress the production of the AMPs." (PMID 29259713, 2017). "In the atopy-like dermatitis mouse model, the expression of Th2 cytokines such as IL-4, IL-5, and IL-10 in the lymph nodes of TMA-treated mice was found to be elevated, and BVA largely abrogated TMA-induced production of Th2 cytokines." (PMID 26825274, 2016). "It acts via a heterodimeric receptor composed of IL-31Rα and oncostatin M receptor β and expression of IL-31 correlates with the expression of IL-4 and IL-13 suggesting that IL-31 is involved in Th2-mediated skin inflammation." (PMID 25756056, 2015). "Our study demonstrates that TEO alleviates key hallmarks of ovalbumin-induced AD-like dermatitis in mice—including chronic pruritus, epidermal hyperplasia, cutaneous dysbiosis, and inflammatory infiltration—through the modulation of IL-4-mediated JAK/STAT signaling." (PMID 41471858, 2025). "The pathogenesis of dermatitis involves epidermal barriers abnormalities, leading to heterogeneous immunological dysregulations predominantly in type 2 immunity (Th2, IL-4, IL-13, IL-31), but also including varying degrees of upregulation of the Th1 (IFN-γ), Th17 (IL-17), and Th22 axes (IL-22)." (PMID 38550585, 2024). "Moreover, the expression levels of inflammatory cytokines IL-4 and IL-13, as well as dermatitis scores, significantly improved after UFB shower treatment in Dfb-induced AD mice." (PMID 39790997, 2024). "Interestingly, we found that cASC-EVs improved AD-like dermatitis and markedly decreased the levels of serum IgE, ear thickness, inflammatory cytokines, and chemokines such as IL-4 and IFN-γ in a dose-dependent manner." (PMID 37444013, 2023). "Therefore, we assessed the role of IL-4 and IL-17 in the development of skin inflammation using WAS−/−IL-4-/- and WAS−/−IL-17−/− mice." (PMID 35265075, 2022).
dermatitis (continued). "The mediators involved in Th2 reactions include IL-4, IL-5, IL-13, IL-33, and IgE, in which IL-4 triggers dermatitis, similar to its effect in AD by inhibiting the production of IFN-gamma, thereby inducing an immune imbalance and increasing the synthesis of IgE." (PMID 36077570, 2022). "AD is a pruritic skin disorder with barrier dysfunction and elevated expression of IL-4 and IL-13." (PMID 35563259, 2022). "Recent transcriptomic analyses have revealed that in AD, gene expression levels of IL-13 correlate more with the intensity of skin inflammation than those of IL-4, suggesting that the IL-13-producing dermal ILC2s may be more involved in the pathogenesis of AD." (PMID 33233866, 2020). "Dermatitis is typically associated with both skin-produced cytokines (e.g., IL-33, -17C, and TSLP), and a skewing of CD4+ T cells into T helper 2 (Th2) and their associated cytokines (e.g., IL-4,-5,-13,)." (PMID 33017398, 2020). "Inhibition of Jak1 and Jak2 by topically applied ruxolitinib or momelotinib successfully decreased inflammation in a hapten-induced hypersensitivity model as well as in TSLP-induced dermatitis in mice together with the down-regulation of mRNA expression of IL-4, IL-5, IFNγ, and TSLP in the skin." (PMID 31447854, 2019). "In addition, a study that used a repeated hapten application to induce AD in mice showed that IL-17A is necessary for the development of skin inflammation, IL-4 production, and IgG1 and IgE induction." (PMID 29259713, 2017). "The HIGH and the LOW phenotypes from the conventional mice were clearly transferred to germ-free mice, as there was a higher expression of dermatitis score, ear thickness, IL-1β, TNFα, IL-4, and IL-6 in the HIGH mice compared to the LOW mice, and for most of these also higher than the CONV mice." (PMID 28290517, 2017). "To address the question whether GMP administration might modulate this Th2 inflammatory response in dermatitis, we examined mRNA changes of IL-4, IL-5, and IL-13 by qRT-PCR in injured skin tissue." (PMID 28265582, 2017). "In addition, transgenic mice expressing epidermal IL-4 have been reported to develop skin inflammation reproducing all key features of human AD." (PMID 29206209, 2017). "Interestingly, GMP administration before AD-induction decreased in 83.56, 96.5, and 88.38% the expression of IL-4, IL-5, and IL-13 in dermatitis skin." (PMID 28265582, 2017). "Xiao-feng-san might also correct the Th1/Th2 balance by preventing the increase in interleukin-4 mRNA expression and the decrease in interferon-gamma mRNA expression to inhibit dermatitis." (PMID 27822287, 2016). "Our results indicated that 7,8,4′-THIF, a metabolite of the soy isoflavone daidzin, suppresses the development of DNCB-induced dermatitis in NC/Nga mice, probably by down-regulating various Th2- (TARC, IL-4, IL-5, and IL-13) and Th1-associated factors (IL-12 and IFN-γ)." (PMID 25170825, 2014). "Similarly, the IL-4 producing cells in patients with dermatitis were increased in the CD4+ and CD8+ T cell population among the peripheral blood mononucleocytes." (PMID 19890385, 2009). "Thus, it will be interesting to examine whether the conjugation of NGO with anti-CD16 antibodies effectively suppresses Th2-mediated skin inflammation by increasing NK cell-derived IFNγ but decreasing Th2 cell-derived IL4." (PMID 39199350, 2024). "Moreover, Lactobacillus plantarum-derived EVs administered orally in a mouse model of AD induced with SA-derived EVs inhibited IL-4 production and its consequent skin inflammation in vivo, resulting in decreased epidermal thickness, albeit no changes in the eosinophilic infiltration." (PMID 38543582, 2024). "In the described study, dermatitis severity, histopathological changes, serum levels of IFN-γ and interleukin 4 (IL-4), and changes in the protein expression of HMGB1 were evaluated by Western blotting." (PMID 38001807, 2023).